PER1 (period circadian regulator 1)
Diseases named in the same sentence as PER1 in open-access papers (continued):
Sharing a sentence is not in itself a finding about the gene and the disease.
lupus nephritis (1 paper, 2021). Glomerulonephritis in the context of systemic lupus erythematosus. "We found modest disruption of renal diurnal rhythm of Rev-erbα and marked dysregulation of both Per1 and Per2 in the nephritic kidneys suggesting that these could be potential targets for circadian modulating therapy in lupus nephritis." (PMID 34488619, 2021).
malaria (1 paper, 2022). Malaria is a serious and sometimes fatal disease caused by a parasite that commonly infects a certain type of mosquito which feeds on humans. "That we do not observe a severe reduction in densities over a single IDC in WT mismatched and Per1/2‐null TRF infections, coupled with revealing malaria parasites adopt option (iv) demonstrates that parasites exert more control over their IDC schedule than negative selection by host rhythms." (PMID 34778983, 2022).
myocardial ischemia (1 paper, 2013). A disorder of cardiac function caused by insufficient blood flow to the muscle tissue of the heart. "Studies on cardiac lactate production during myocardial ischemia confirm a non-redundant role of Per1 and Per2 for cardiac metabolism, where lactate production is linked to Per2 but not Per1." (PMID 23977055, 2013). "To test the hypothesis that cardiac Per2 represents an important regulator of cardiac metabolism during myocardial ischemia, we measured lactate during reperfusion in Per1−/−, Per2−/− or wildtype mice." (PMID 23977055, 2013).
myopia (1 paper, 2021). "PER1 is expressed in the inner nuclear layer of the retina harboring amacrine cells, which were implicated in optical defocus detection and myopia development." (PMID 34107987, 2021).
obstructive sleep apnea syndrome (1 paper, 2021). Cessation of air flow during sleep due to upper airway obstruction. "A study reported circadian gene dysfunction in patients with obstructive sleep apnea syndrome, particularly changes in Per1 mRNA expression." (PMID 34275002, 2021).
oral mucositis (1 paper, 2021). Inflammation of the mucous membranes of any of the structures in the mouth. "Therefore, we expect PER1 expression to be positively associated with radiation sensitivity and radiation-induced oral mucositis." (PMID 34221066, 2021).
overnutrition (1 paper, 2025). An imbalanced nutritional status resulting from excessive intake of nutrients. "For the group exposed to maternal overnutrition and nutritional challenge, the only significant changes in the duodenum were observed at the onset of the dark phase, with a downregulation in the expression of Per1 in comparison to that in the control group." (PMID 40427730, 2025).
periodontitis (1 paper, 2024). An acute or chronic inflammatory process that affects the tissues that surround and support the teeth. "Furthermore, quercetin may repair oxidative stress damage to OMSCs by modulating the mRNA changes of m6A‐modified Per1, regulating the oxidative stress milieu in periodontitis, and facilitating bone defect healing." (PMID 38749005, 2024).
polycystic ovary syndrome (1 paper, 2025). A disorder that manifests as multiple cysts on the ovaries. "A study suggested that PER1 promotes ferroptosis and dysfunctional lipid metabolism in granulosa cells in polycystic ovary syndrome (PCOS) by inhibiting sterol regulatory element-binding factor 2 (SREBF2)/arachidonate 15-lipoxygenase (ALOX15) signaling pathway." (PMID 41451215, 2025).
renal carcinoma (1 paper, 2021). A carcinoma arising from the epithelium of the renal parenchyma or the renal pelvis. "However, the expression levels of PER1, PER2 in KIRC and CRY2 in KICH were significantly increased in tumor tissues, and they suggested subsequent in-depth investigation of the mechanisms underlying circadian abnormalities in these three renal carcinomas." (PMID 34977153, 2021).
serous cystadenoma (1 paper, 2023). A serous neoplasm in which the cysts and papillae are lined by a single layer of cells without atypia, architectural complexity or invasion. "Among the samples from transcriptome analysis, PER1 was the most downregulated TSG in the Indian cohort except for serous cystadenoma and from literature, its levels correlate with infiltrating neutrophils, regulatory T cells, and M2 macrophages, which was evident in the Indian cohort." (PMID 37091785, 2023).
Shock (1 paper, 2021). The state in which profound and widespread reduction of effective tissue perfusion leads first to reversible, and then if prolonged, to irreversible cellular injury. "Additionally, we found that NR1D1, NR1D2, CRY1, CRY2, PER1, PER2 and DBP had altered rhythms in at least some patients with septic shock." (PMID 33900485, 2021).
sleeping sickness (1 paper, 2018). "Curiously, in a previous study using a rat model for sleeping sickness, researchers found a ~30-min period shortening in the pituitary gland using a Per1-luc reporter, but not in the SCN38." (PMID 29302035, 2018).
status epilepticus (1 paper, 2018). Status epilepticus is defined as a continuous seizure lasting more than 30 min, or two or more seizures without full recovery of consciousness between any of them. "In this study, we systematically evaluated the temporal expression of seven core circadian transcripts (Bmal1, Clock, Cry1, Cry2, Per1, Per2, and Per3) and the spontaneous locomotor activity (SLA) in post-status epilepticus (SE) model of mTLE." (PMID 30116220, 2018).
stomach adenocarcinoma (1 paper, 2023). "A study on stomach adenocarcinoma has revealed opposite results, where high NR1D1 and PER1 levels were correlated with poor OS." (PMID 37373286, 2023).
thyroid (1 paper, 2021). "We then chose CLOCK, BMAL1, CRY1, CRY2, PER1 and PER2 to observe the changes of circadian rhythm genes in thyroid malignant tissues." (PMID 34211057, 2021).
vitamin A deficiency (1 paper, 2022). Deficiency of vitamin A due to malnutrition, malabsorption, or dietary lack. "Vitamin A deficiency reduced the level of RXRβ mRNA, changed the rhythm amplitude of the PER1, REV-ERB genes and REV-ERB protein, and phase-shifted the daily peaks of RORα protein as well as BMAL1, RORα, RC3 and BDNF mRNA levels." (PMID 36466383, 2022).
ZIKV infection (1 paper, 2025). "To determine activation of the IRE1 endonuclease activity through the RIDD branch during ZIKV infection in human microglia, we measured expression of canonical RIDD targets Bloc1s1, Scara3, and Per1." (PMID 41157563, 2025).
tumor (140 papers, 2010 to 2026). "Period circadian regulator 1 (PER1) mutations enhance glycolytic flux and tumor progression via the receptor for activated C kinase 1 (RACK1)/PI3K/AKT pathway." (PMID 40725147, 2025). "The period circadian regulator PER1, for example, promotes ferroptosis by downregulating hypoxia-inducible factor-1α (HIF-1α), thereby increasing ROS and lipid peroxidation; loss of PER1 expression suppresses ferroptosis and accelerates tumor progression." (PMID 41227330, 2025). "Increased expression of ALKBH5 restrains tumor proliferation, migration, and invasion, and inhibits tumor growth in vivo, a process intricately linked to period circadian regulator 1(PER1)." (PMID 39791162, 2025). "The circadian clock regulates the osteogenic potential by inhibiting BMAL1 expression, and the impaired expression of BMAL1 and PER1–2 causes tumor growth in mouse embryonic tissue." (PMID 41234239, 2025). "PER1 expression levels are associated with tumor immune infiltration, participating in immune evasion by influencing immune factor expression and immune cell recruitment." (PMID 41451215, 2025). "In mice, Per1 and Per2 were identified as tumor suppressors, while PER2-deficient animals had an increased risk of genetic and UV-induced cancer." (PMID 39519024, 2024). "We then identified which immune cells subtypes present in the tumor infiltration were associated with the expression of the three CCGs, PER-1, CRY2, and NPAS2 and the prognosis of HCC." (PMID 36118525, 2022). "Our findings reveal an important role of PER1 in OV and also clarify the potential relationship of PER1 with tumor immunity and its underlying mechanism." (PMID 34220965, 2021). "Downregulation of PER3 and upregulation of TIMELESS (TIM) were characteristic for larger tumors, downregulation of PER3 for deeper tumor invasion and downregulation of PER1 and PER3 was associated with poor patient survival." (PMID 30760278, 2019). "Based on that, 9 out of the identified 14 candidate genes passed our criteria, i.e., showed a highly significant (i.e., p < 0.001) association with their gene expression in one or more tumor entities like PER1 and POLD1." (PMID 29445424, 2018). "The specific mechanism underlying aberrant expression and altered rhythm of PER1 leading to tumorigenesis and tumor development still needs further investigation." (PMID 23405233, 2013). "PER2-deficient mice are more susceptible to genetic or radiation-induced cancer, Per1 or Per2 over-expression reduces tumor growth in vivo and promotes apoptosis in vitro, while PER down-regulation promotes cancer cell growth [46-48, 52-54 (but see 56, 57)]." (PMID 21566258, 2011). "Consequently, low levels of PER1 have been linked to a higher likelihood of tumor initiation and growth in LC." (PMID 39812541, 2025). "In tumors, the low expression of PER1 may be associated with the regulation of tumor cell proliferation, invasion, and apoptosis." (PMID 41451215, 2025). "Genes associated with the circadian rhythm (e.g., Period 1/2 (Per1, Per2)), inflammatory factors and tumor immune factors may be related to the occurrence and development of ovarian cancer." (PMID 33083827, 2020).
tumor (continued). "A higher incidence of tumor development was observed in PER1-deficient mice than in wild-type mice." (PMID 31350984, 2019). "Aberrant suppression of PER1 is strongly linked to carcinogenesis and tumor development." (PMID 26943040, 2016). "Thus, the specific core clock genes Per2 and Per1 are considered as tumor suppressors linked to tumor numbers and cancer growth rates." (PMID 26541675, 2015). "Tumor growth, gene expression of Per1, Per2, Per3, and Rev-Erbα, and TNF-α concentrations were analyzed at six circadian time points." (PMID 41736190, 2026). "In the context of DNA damage, a tumor suppressive function has been suggested for the three PER genes (PER1, PER2, PER3)." (PMID 40352720, 2025). "Accordingly, the Overall ESTIMATE score (p = 2.763e-4, q = 0.0146) was significantly lower in High PER1 patients, indicating a higher level of tumor cell purity." (PMID 40715535, 2025). "Silencing PER1 leads to ferroptosis resistance and accelerated tumor progression in xenograft models." (PMID 41227330, 2025). "Abnormal expression of PER1 disrupts cell cycle progression, inhibits DNA damage repair, and affects tumor development by regulating cell proliferation and apoptosis." (PMID 41451215, 2025). "PER1 (period 1), one of circadian clock genes, was expressed at low levels in multiple cancers and reported to be involved in tumor progression and prognosis via multiple biological pathways, in particular via DDR pathways and cell apoptosis." (PMID 38556856, 2024). "In vivo xenograft tumor assays revealed that PER1 KO reduced tumor volumes and weights in HCC-bearing mice." (PMID 38245510, 2024). "The promotion of cancer cell growth in vitro and the enhancement of time-dependent tumor growth in vivo occur exclusively during specific periods of the day, as a result of the downregulation of either Per1 or Per2." (PMID 39012661, 2024). "For instance, Per1 has been shown to enhance DNA damage repair and apoptosis, thereby exerting tumor suppressive effects." (PMID 39012661, 2024). "At specific times of the day, PER1 has a tumor suppressor function that diminishes the proliferation of cancer cells and tumor growth." (PMID 38892035, 2024). "The circadian amplitude of the two daily tumor growth peaks is improved by a decrease in PER1 expression." (PMID 38892035, 2024). "More importantly, given PER1 is a central clock gene that controls circadian homeostasis, it is imperative to examine the true role of PER1 in tumor progression under circadian conditions." (PMID 38245510, 2024). "For instance, CLOCK and PER3 were preferentially expressed in tumour and stomal cells, while PER1 was selectively expressed in immune cells and stromal cells but not in cancer cells." (PMID 39201344, 2024). "Loss of ALKBH5 reduces Period Circadian Regulator 1 (PER1) expression in a YTHDF2-dependent manner, promoting tumor migration, invasion, proliferation, and growth." (PMID 39342406, 2024). "Further studies are needed to figure out how PER1 inhibits tumor growth via affecting different immune cell infiltration." (PMID 39043735, 2024). "TUBB2B regulated the expression of TNF-a, IL-6, and PD-1/PD-L1 through the inhibit tumor invasion gene PER1." (PMID 37719786, 2023). "Consistent with the nCV analysis, we found that rAMP decreased substantially in every core clock gene from normal to tumor, as evidenced by PER1 and PER3 expression." (PMID 37262074, 2023). "Per1-/-, Per2-/-, Cry1-/-, Cry2-/- andBmal1-/- mice presented with increased spontaneous and radiation-induced tumor development." (PMID 39282509, 2023).
tumor (continued). "PER1 is important in the maintenance of the circadian rhythm in cells, and its down-regulation can enhance tumor growth." (PMID 36439444, 2022). "The abnormal expression of PER1 has been shown in various types of cancers, and both oncogenic and tumor-suppressive roles of PER1 have been revealed." (PMID 35936737, 2022). "This evidence is consistent with the known role of PER1 as a suppressor of clock and tumor-related genes." (PMID 34237069, 2021). "The PER family is generally considered to have a tumor suppressor effect, and the mechanisms behind the tumor suppressing effects of PER1 and PER2 are clear." (PMID 34285836, 2021). "Future studies are needed in order to provide a better understanding of the role of PER1 in the cellular response to anticancer treatments in normal and tumor cells." (PMID 33804124, 2021). "Current studies indicate that the clock gene PER1 is downregulated in a variety of tumors and plays an important part in promoting tumor progression." (PMID 34220965, 2021). "We first used the Oncomine database to explore the expression levels of PER1 in different tumor types." (PMID 34220965, 2021). "Tumour progression (TNM stage) correlated with PER1 (p = 0.020), and early-stage tumours (stage I + stage II) showed a higher expression of such proteins than those of advanced stage (stage III + stage IV)." (PMID 34440171, 2021). "In vivo tumorigenicity assays confirmed that PER1 overexpression inhibited tumor growth while suppressing glycolysis, proliferation, and the PI3K/AKT pathway." (PMID 33723221, 2021). "This study is of great significance for elucidating the biological function of the circadian clock gene PER1 and its tumor-inhibition mechanism in OSCC and provides a basis for further study of PER1 as a potential target for the treatment of OSCC." (PMID 33723221, 2021). "This study observed that Per1 levels show a circadian expression pattern in both normal and tumor tissues." (PMID 34361055, 2021). "The suppression of the rates of cell proliferation and invasion indicated a PER1-dependent anti-tumour function of ALKBH5 in PC progression." (PMID 32429928, 2020). "HNF1A, ESR1, and FLT4 were mutated significantly more frequently in tumor tissue samples obtained from patients with stage III BC, while SYNE1, PER1, and LRP1B were mutated significantly more frequently in stage IV BC." (PMID 32731384, 2020). "In two different mouse models of cancer we find that expression of the core clock gene Per2 in the TME is crucial for tumor initiation and metastatic colonization, whereas another core gene, Per1, is dispensable." (PMID 33123539, 2020). "Again, the Per1/2−/− mice displayed significantly less tumor growth relative to saline treatment, especially with morning cisplatin treatment, crossing the 5-fold increase mark by day 14, 2 days later than the wild-types." (PMID 29581861, 2018). "In the tumor-bearing mice, tumor-infiltrating lymphocytes were significantly higher in Per1/2−/− mice than in wild-type mice, with a 6.9-fold and 5.4-fold increase for CD4+ and CD8+ T cell populations, respectively." (PMID 29581861, 2018). "In tumor development, PER1 suppresses expression levels of tumor-related genes including c-MYC gene." (PMID 29570674, 2018). "Per1 is reduced in cancer tissue and its inhibition blunts apoptosis, whereas Per2 represses tumor in breast cancer and induces estradiol (E2) in mammary cells." (PMID 29607311, 2018). "Per1- and Per2-mediated tumor-repressing effect is more specific to early light and early dark phase." (PMID 29607311, 2018).